MLST8 (MTOR associated protein MLST8)
Description:
Subunit of both mTORC1 and mTORC2, which regulates cell growth and survival in response to nutrient and hormonal signals. mTORC1 is activated in response to growth factors or amino acids. In response to nutrients, mTORC1 is recruited to the lysosome membrane and promotes protein, lipid and nucleotide synthesis by phosphorylating several substrates, such as ribosomal protein S6 kinase (RPS6KB1 and RPS6KB2) and EIF4EBP1 (4E-BP1). In the same time, it inhibits catabolic pathways by phosphorylating the autophagy initiation components ULK1 and ATG13, as well as transcription factor TFEB, a master regulators of lysosomal biogenesis and autophagy. The mTORC1 complex is inhibited in response to starvation and amino acid depletion. Within mTORC1, MLST8 interacts directly with MTOR and enhances its kinase activity. In nutrient-poor conditions, stabilizes the MTOR-RPTOR interaction and favors RPTOR-mediated inhibition of MTOR activity. As part of the mTORC2 complex, transduces signals from growth factors to pathways involved in proliferation, cytoskeletal organization, lipogenesis and anabolic output. mTORC2 is also activated by growth factors, but seems to be nutrient-insensitive. In response to growth factors, mTORC2 phosphorylates and activates AGC protein kinase family members, including AKT (AKT1, AKT2 and AKT3), PKC (PRKCA, PRKCB and PRKCE) and SGK1. mTORC2 functions upstream of Rho GTPases to regulate the actin cytoskeleton, probably by activating one or more Rho-type guanine nucleotide exchange factors. mTORC2 promotes the serum-induced formation of stress-fibers or F-actin. mTORC2 plays a critical role in AKT1 activation by mediating phosphorylation of different sites depending on the context, such as 'Thr-450', 'Ser-473', 'Ser-477' or 'Thr-479', facilitating the phosphorylation of the activation loop of AKT1 on 'Thr-308' by PDPK1/PDK1 which is a prerequisite for full activation. mTORC2 regulates the phosphorylation of SGK1 at 'Ser-422'. mTORC2 also modulates the phosphorylation of PRKCA on 'Ser-657'. Within mTORC2, MLST8 acts as a bridge between MAPKAP1/SIN1 and MTOR.
Synonyms: GBL; LST8; Pop3; GbetaL; WAT1
Tractability: Small molecule: a drug acting on it is in phase 2 or 3 trials; a structure with a bound ligand is known; a high-quality ligand is known. PROTAC: UniProt records ubiquitination sites on it; ubiquitination databases record sites on it; its protein half-life has been measured; a small molecule that binds it is known.
Gene: Protein-coding gene on chromosome 16 (2,204,248 to 2,209,453, forward strand). Ensembl gene ENSG00000167965.
Subcellular location: Lysosome membrane; Cytoplasm
Subcellular location (Human Protein Atlas): Nucleoplasm; Cell Junctions; Golgi apparatus
Pathways (Reactome):
Signal Transduction: Energy dependent regulation of mTOR by LKB1-AMPK; MTOR signalling; PIP3 activates AKT signaling; Regulation of PTEN gene transcription; VEGFR2 mediated vascular permeability; mTORC1-mediated signalling
Cellular responses to stimuli: Amino acids regulate mTORC1; HSF1-dependent transactivation; High laminar flow shear stress activates signaling by PIEZO1 and PECAM1:CDH5:KDR in endothelial cells
Disease: Constitutive Signaling by AKT1 E17K in Cancer; Dengue virus modulates apoptosis
Autophagy: Macroautophagy
Immune System: CD28 dependent PI3K/Akt signaling
Gene Ontology:
Molecular function: protein binding; protein serine/threonine kinase activator activity; protein serine/threonine kinase activity; protein-macromolecule adaptor activity
Biological process: positive regulation of TOR signaling; regulation of actin cytoskeleton organization; TORC1 signaling; TORC2 signaling; cellular response to hypoxia; cellular response to nutrient levels; cellular response to osmotic stress; cytoskeleton organization; DNA damage response; negative regulation of apoptotic process; negative regulation of autophagy; positive regulation of cell growth; positive regulation of glycolytic process; positive regulation of lipid biosynthetic process; positive regulation of pentose-phosphate shunt; TOR signaling
Cellular component: lysosomal membrane; TORC1 complex; TORC2 complex; cytoplasm; cytosol; nucleoplasm
Genetic constraint (gnomAD): Loss-of-function variants: 20 observed, 42.81 expected, observed/expected ratio (o/e) 0.47, 90% interval 0.33 to 0.68. The synonymous counts are far from expectation, so gnomAD's model fits this gene poorly and the ratio says little. Missense variants: 422 observed, 472.16 expected, observed/expected ratio (o/e) 0.89, 90% interval 0.82 to 0.97. Synonymous variants: 243 observed, 188.78 expected, observed/expected ratio (o/e) 1.29, 90% interval 1.16 to 1.43.
Homologues: Orthologues: guinea pig MLST8 (99% identical), macaque MLST8 (99% identical), dog MLST8 (99% identical), pig MLST8 (99% identical), mouse Mlst8 (98% identical), rat Mlst8 (98% identical), zebrafish mlst8 (92% identical), tropical clawed frog mlst8 (91% identical), chimpanzee MLST8 (89% identical), rabbit MLST8 (67% identical), Drosophila melanogaster Lst8 (48% identical), Caenorhabditis elegans mlst-8 (27% identical).
Diseases named in the same sentence as MLST8 in open-access papers:
MLST8 is named in the same sentence as 36 diseases in open-access papers, as found by Europe PMC text mining. Sharing a sentence is not in itself a finding about the gene and the disease. The quoted sentences say what the papers report.
glioblastoma (6 papers, 2018 to 2025). The most malignant astrocytic tumor (WHO grade IV). "For instance, YBX1 has been shown to bind to the 5′-UTR of CCT4 mRNA and promote its translation, thereby facilitating glioblastoma development through mLST8 folding and activation of the mTOR signaling pathway." (PMID 40819060, 2025). "Taken together, our results show that we have identified the YB-1/CCT4/mLST8/mTOR axis as a contributor to glioblastoma growth and suggest a therapeutic approach to target this axis using competitive RNA oligonucleotides." (PMID 35239512, 2022). "Taken together, these findings uncover a disrupted proteostasis pathway involving a YB-1/CCT4/mLST8/mTOR axis in promoting glioblastoma growth, suggesting that YB-1 is a potential therapeutic target for the treatment of glioblastoma." (PMID 35239512, 2022). "In glioma, YBX1 may act as an important activator of the mTOR signaling pathway and mediate the YBX1/CCT4/mLST8/mTOR axis to promote the growth of glioblastomas." (PMID 38849679, 2024). "CCT4 may facilitate glioblastoma cell growth by involving the YB-1/CCT4/mLST8/mTOR signaling pathway." (PMID 37006287, 2023). "The YB-1/CCT4/mLST8/mTOR axis promotes glioblastoma growth in vivo." (PMID 35239512, 2022). "The YB-1/CCT4/mLST8/mTOR pathway is upregulated in patients with glioblastoma." (PMID 35239512, 2022). "YB-1 maintains the self-renewal of glioblastoma stem–like cells via the CCT4/mLST8 cascade." (PMID 35239512, 2022). "In patients with glioblastoma, high protein expression of YB-1 correlated with increased expression of CCT4 and mLST8 and activated mTOR signaling." (PMID 35239512, 2022). "Next, we surveyed the expression of YB-1, CCT4, mLST8, and phospho-S6K1 (T389) using a cohort of glioblastoma patient samples by performing IHC assays." (PMID 35239512, 2022). "However, in glioblastoma cells, we found that only the expression of mLST8 protein was regulated by CCT, but not RAPTOR (data not shown), suggesting that CCT promotes the folding of its substrate in a cell-type-dependent manner." (PMID 35239512, 2022). "Moreover, higher levels of CCT4, mLST8, and activated S6K1 predicted a poor survival, similarly to YB-1, implying that YB-1 may serve as a promising target for the treatment of glioblastoma." (PMID 35239512, 2022).
breast carcinoma (4 papers, 2021 to 2023). "Importantly, survival analysis demonstrates that high MLST8 expression is significantly associated with poorer overall survival in breast cancer patients." (PMID 34529665, 2021). "Our results further support the essential role of MLST8 in enabling both mTORC1 and 2’s activity and suggest MLST8 as a viable therapeutic target in breast cancer." (PMID 34529665, 2021). "Together, these results indicate MLST8 plays a tumour-enhancing role in breast cancer and its expression may serve as a prognosis indicator, in line with its reported role in other tumour types." (PMID 34529665, 2021). "Furthermore, our results demonstrate that MLST8 is required for the assembly and activity of both MTOR complexes and suggest MLST8 is a viable therapeutic target in breast cancer." (PMID 34529665, 2021). "However, the function of MLST8 and SPNS1 in breast cancer was still unknown." (PMID 33796128, 2021).
prostate carcinoma (4 papers, 2015 to 2021). A carcinoma that arises from epithelial cells of the prostate gland. "On the other hand, MLST8 stabilizes the raptor-MTOR interaction and promotes mTORC1 activity, and upregulation of MLST8 enhances mTORC1/2 activities in colon carcinoma and prostate cancer." (PMID 34529665, 2021). "In this study, we show that mLST8 is also upregulated in several human colon and prostate cancer cells/tissues, in which it contributes to tumor growth and invasion." (PMID 25906254, 2015). "In this study, we found that the expression of mLST8, a required subunit of both mTOR complex 1 (mTORC1) and complex 2 (mTORC2), was upregulated in several human colon and prostate cancer cell lines and tissues." (PMID 25906254, 2015). "Previous studies have revealed that mLST8 was upregulated in human colon and prostate cancer cells and contributed to tumor progression by activating the mTORC1 complex and its effector protein including translation initiation factor 4E-binding protein 1 (4E-BP1) (Yang and Guan." (PMID 31641854, 2020). "We next examined mLST8 expression in several lines of colon and prostate cancer cells." (PMID 25906254, 2015). "Knockdown of mLST8 significantly suppressed mTORC1 and mTORC2 complex formation, and it also inhibited tumor growth and invasiveness in human colon carcinoma (HCT116) and prostate cancer (LNCaP) cells." (PMID 25906254, 2015). "In the case of prostate cancers, however, there was no significant change in the expression of mLST8 transcripts between normal and cancer cells." (PMID 25906254, 2015). "In prostate cancers, however, there was no significant change in the levels of transcripts between cancer and normal cells, suggesting that mLST8 expression may instead be regulated by protein stability in these cells." (PMID 25906254, 2015).
colon carcinoma (3 papers, 2015 to 2023). "Furthermore, RT-PCR analysis of mLST8 mRNA levels revealed that mLST8 expression is regulated at the level of transcription in colon cancers." (PMID 25906254, 2015). "In colon cancers, the levels of mLST8 transcripts were elevated, suggesting that activation of some transcription factors and/or silencing of particular microRNAs may be involved in mLST8 upregulation, as observed for other components of the mTOR complexes." (PMID 25906254, 2015).
glioma (2 papers, 2022 to 2024). A benign or malignant brain and spinal cord tumor that arises from glial cells (astrocytes, oligodendrocytes, ependymal cells). "We applied the GSC model to obtain a deeper understanding of the role of the YB-1/CCT4/mLST8/mTOR axis in glioma growth." (PMID 35239512, 2022).
acute myeloid leukemia (1 paper, 2022). Acute myeloid leukemia (AML) is a group of neoplasms arising from precursor cells committed to the myeloid cell-line differentiation. "Here, we set out to investigate the potential of the BP-regulated ALKBH5/MLST8/EIF4EBP1 axis on prevention and treatment of acute myeloid leukemia (AML)." (PMID 35579750, 2022). "Our data indicate that BP can inhibit acute myeloid leukemia cell proliferation by downregulating ALKBH5-mediated m6A demethylation of EIF4EBP1 and MLST8 mRNAs, which may have potential to prevent and treat this disease." (PMID 35579750, 2022).
clear cell renal cell carcinoma (1 paper, 2024). "It is noteworthy that mLST8 is up-regulated in clear cell renal cell carcinoma and the FBXW7-mediated ubiquitination and degradation of mLST8 prevents tumor progression." (PMID 38270460, 2024).
Cognitive impairment (1 paper, 2018). Abnormal cognition is characterized by deficits in thinking, reasoning, or remembering. "In addition, the combination of PTPN1, COPZ1, FAXDC2, EFTUD2 and MLST8 is a useful signature for cognitive impairment." (PMID 29896099, 2018).
liver cancer (1 paper, 2014). An epithelial or non-epithelial malignant neoplasm that arises from the liver. "RANBP10, IRF1 and ZNF395 were found to be down-regulated in liver cancer tissues, while the expression levels of NACC1 and MLST8 remained unchanged." (PMID 24599008, 2014).
lymph node metastasis (1 paper, 2020). "The results confirmed that BM patients with lymph node metastasis (N2/3) tended to have polymorphisms of rs26865 and rs3160 in mLST8." (PMID 31641854, 2020). "We found that rs26865 and rs3160 polymorphic variants of mLST8 were significantly associated with the risk of BM, particularly among those with lymph node metastasis (N2/3), high CEA and SCC antigen level, and high Ki-67 proliferation index and gene mutation frequency." (PMID 31641854, 2020).
malaria (1 paper, 2022). Malaria is a serious and sometimes fatal disease caused by a parasite that commonly infects a certain type of mosquito which feeds on humans. "While malaria parasites have lost most of the TORC components through genomic reduction, including mTOR, mLST8, Raptor, and Rictor, the parasites are able to control protein synthesis via various mechanisms of translational regulation." (PMID 35889137, 2022).
pulmonary fibrosis (1 paper, 2024). Chronic progressive interstitial lung disorder characterized by the replacement of the lung tissue by connective tissue, leading to progressive dyspnea, respiratory failure, or right heart failure. "YAP1/TAZ activated or inhibited genes expression in the mitochondrial quality control pathway by binding to the promoter regions of mTOR, Raptor and mLST8, thereafter accelerating the fibroblast–myofibroblast differentiation and extracellular matrix deposition to promote pulmonary fibrosis." (PMID 38159063, 2024).
retinal degeneration (1 paper, 2025). Degeneration of the retina. "mLST8 overexpression in RPE cells upregulates mTORC1/2, causing autophagy deregulation, metabolic alterations, and reduced melanosome function, leading to retinal degeneration." (PMID 39957408, 2025). "By generating a mouse model with RPE‐specific constitutive KI of mLST8, a subunit essential for both mTORC1 and mTORC2, we observed significant retinal and RPE abnormalities leading to retinal degeneration." (PMID 39957408, 2025).
sarcoma (1 paper, 2016). A usually aggressive malignant neoplasm of the soft tissue or bone. "The total levels of mTORC1 components mTOR, Raptor and mLST8 in cell lysates were not altered in IS treated sarcoma cells." (PMID 27056897, 2016).
viral infection (1 paper, 2023). "We previously found significant enrichment of the host factor mLST8 in a CRISPR screen, suggesting that mLST8 plays an important role during viral infection." (PMID 37377422, 2023).
tumor (19 papers, 2015 to 2025). "Similar reductions in glycolytic ECAR and extracellular lactate are observed in MLST8-deficient H596 and KLN205-Ptennull Mlst8-KO cells, while lactate levels were decreased in tumor interstitial fluid of KLN205-Ptennull Mlst8-KO tumors." (PMID 40640525, 2025). "In H596 cells, loss of MLST8 reduced tumor growth that was also associated with reduced cell viability in vitro." (PMID 40640525, 2025). "Collectively, these data indicate that Mlst8/mTORC2 loss in tumor cells enhances CD8+ T cells effector function and antitumor immune response." (PMID 40640525, 2025). "To investigate the mechanism underlying mLST8-mediated promotion of tumor growth, we assessed the effects of mLST8-KD on the formation of mTOR complexes and the activity of downstream signaling components in HCT116 and LNCaP cells." (PMID 25906254, 2015). "Interestingly, loss of MLST8/mTORC2 signaling also decreases the expression of PSGL-1 on tumor cells, serving to further influence T cell activity through VISTA." (PMID 40640525, 2025). "To determine the role of mTORC2 in LUSC in vivo tumor growth, we injected WT or MLST8-KO tumor cells into the flanks of recipient mice." (PMID 40640525, 2025). "Introduction of CCT4 or mLST8 into YB-1–knockdown cells partially rescued in vivo tumor cell growth and the intratumoral activity of both mTOR1 and mTOR2 signaling." (PMID 35239512, 2022). "In conclusion, we found that BP can inhibit AML cell proliferation and tumor growth by downregulating ALKBH5 to repress m6A demethylation of MLST8/EIF4EBP1 mRNA." (PMID 35579750, 2022). "As a result, loss of mLST8 ubiquitination by either mutating the K305/K313 or depleting the E3 ligase TRAF2 enhances mTORC2 activation and tumor growth, while knockout of the deubiquitinase OTUD7B exhibits opposite phenotypes." (PMID 33670113, 2021). "Further, knockdown of MLST8 suppresses tumor growth by inhibiting MTOR complex formation and activity." (PMID 34529665, 2021). "In conclusion, we have demonstrated a crucial role for mLST8-mediated upregulation of the mTOR pathway in promoting tumor progression." (PMID 25906254, 2015). "In this study, we addressed the role of mLST8, a requisite component of mTOR complexes, in tumor progression." (PMID 25906254, 2015). "Our results suggest that mLST8 plays distinct roles in normal and cancer cells, depending on its expression level, and that upregulation of mLST8 contributes to tumor progression by activating both the mTORC1 and mTORC2 pathways." (PMID 25906254, 2015). "To evaluate the role of mLST8 upregulation in cancer cells, we examined the effects of shRNA-mediated knockdown of mLST8 (mLST8-KD) on tumor growth of HCT116 and LNCaP cells." (PMID 25906254, 2015). "We observed a significantly increased in tumor cell killing with Mlst8-KO compared to control." (PMID 40640525, 2025). "To investigate how mTORC2 may regulate SELPLG/PSGL-1 expression in tumor cells, we found that MLST8-KO cells exhibited a significant decrease in expression of EPAS1, the gene encoding HIF2α which was previously shown to be regulated by mTORC2." (PMID 40640525, 2025). "However, mLST8 upregulation has been observed in certain types of cancers, contributing to tumor progression by constitutively activating both mTORC1 and mTORC2 pathways." (PMID 39957408, 2025). "The protein encoded by the mammalian lethal with SEC13 protein 8 (MLST8) gene, also known as G protein beta subunit-like (GBL), promotes tumor cell growth and development by regulating mTOR (mechanistic target of rapamycin) signaling and thus does not significantly affect normal cell growth." (PMID 39170695, 2024). "In addition to exerting effects on tumor growth, mLST8-KD also induced dramatic morphological changes in HCT116 cells." (PMID 25906254, 2015). "Therefore, it is likely that upregulation of mLST8 induces full activation of mTORC1/2, resulting in activation of the downstream substrates that are required for tumor progression." (PMID 25906254, 2015).